SLC1A3 (solute carrier family 1 member 3)
Diseases named in the same sentence as SLC1A3 in open-access papers (continued):
Sharing a sentence is not in itself a finding about the gene and the disease.
migraine (11 papers, 2017 to 2024). "Initial results identified significant associations between migraine and rs3776578 (p = 0.04) and rs16903247 (p = 0.05) genotypes within the SLC1A3 gene, which encodes the EAAT1 glutamate transporter." (PMID 38927733, 2024). "In a young man with migraine with aura including hemiplegia, we identified a novel SLC1A3 mutation that predicts the substitution of a conserved threonine by proline at position 387 (T387P) in hEAAT1." (PMID 29066757, 2017). "The minor alleles of both SNPs show a protective effect on migraine risk, which may be conferred via influencing the expression of SLC1A3." (PMID 38927733, 2024). "While only a few hemiplegic migraine cases have been reported with SLC1A3 variants, one of these had a p.Thr387Pro change in this same region of the protein, which resulted in a loss of function effect on the transporter, impairing both K+ binding as well as its trafficking to the membrane." (PMID 33126486, 2020). "In this study, we further examined the channelopathic nature of a migraine through the analysis of common genetic variants in three selected ion channel or transporter genes: SLC4A4, SLC1A3, and CHRNA4." (PMID 38927733, 2024). "More recently, SLC1A3 missense mutation T387P, shown to diminish potassium binding to EAAT1, was identified in a patient with hemiplegic migraine, strengthening the believe that EAAT1 might be involved in hemiplegic migraine." (PMID 32503413, 2020). "In recent years several genes have been put forward as possible hemiplegic migraine genes (i.e. PRRT2, SLC1A3 and SLC4A4), but evaluation of available data should cast doubt on such claims." (PMID 32503413, 2020).
Anxiety (7 papers, 2015 to 2026). Intense feelings of nervousness, tension, or panic often arise in response to interpersonal stresses. "Examining the mRNA SLC1A2, SLC1A3, GRM5, GRIN2B, GRIN2C, GRIA1, CHRNA7, 5-HT2A, and 5-HT3A offers insight into the neurotransmission systems implicated in NP-related anxiety." (PMID 41515464, 2026).
attention deficit-hyperactivity disorder (4 papers, 2018 to 2025). A disorder characterized by a marked pattern of inattention and/or hyperactivity-impulsivity that is inconsistent with developmental level and clearly interferes with functioning in at least two settings (e.g. at home and at school). "In the literature, SLC1A3 mutations have been linked with neurodevelopmental disorders, especially Attention-Deficit/Hyperactivity Disorder (ADHD)." (PMID 41300812, 2025). "At the 5p13 SNP cluster, the nearest gene is SLC1A3, a brain expressed glutamate transporter which has been implicated in some behavioral phenotypes, e.g., attention deficit hyperactivity disorder, mood disorders, cortico-limbic connectivity during affective regulation." (PMID 34518958, 2021).
gastric cancer (4 papers, 2023 to 2025). A primary or metastatic malignant neoplasm involving the stomach. "SLC1A3 (EAAT1) activates the PI3K/AKT pathway in gastric cancer, promoting tumor growth, with high expression correlating with poor prognosis." (PMID 41425581, 2025). "For example, SLC1A3 through the PI3K/AKT pathway to hasten the growth of gastric cancer." (PMID 38230216, 2024).
melanoma (4 papers, 2018 to 2025). A malignant, usually aggressive tumor composed of atypical, neoplastic melanocytes. "On the other hand, three genes (MAFB, NUPR1, and SLC1A3), which were upregulated following combination therapy, showed low expression in the melanoma TCGA cohort." (PMID 38594618, 2024). "Extracellular glutamate and aspartate, produced by neuronal activity, are taken up by melanoma cells via the transporters EAAT1/2 and SLC1A3 and are converted into TCA cycle intermediates via the action of transaminases (GOT1/2)." (PMID 41463339, 2025).
bipolar disorder (3 papers, 2019 to 2026). A disorder of the brain that causes unusual shifts in mood, energy, activity levels and the ability to carry out day-to-day tasks. "Slc1a3, encoding a GABA transporter, has also been formally associated to be more expressed in males with Manic Depressive Disorder and is considered a candidate gene for targeting anxiety disorders, was also activated in Oprm1-positive striatal cells following morphine withdrawal." (PMID 36534642, 2022).
cognitive deficits (3 papers, 2015 to 2023). "We observed the increased expression of Slc1a3, the EAAT1, in 3xTg-AD mice exposed to alcohol, which appears consistent with the increased excitatory/inhibitory balance in AD patients, leading to cortical and hippocampal hyperexcitability and cognitive impairment." (PMID 37308288, 2023).
diabetic retinopathy (3 papers, 2019 to 2025). "And SLC1A3 is mainly involved in diabetic retinopathy in diabetic complications." (PMID 36911691, 2023).
hemiplegic migraine (3 papers, 2011 to 2021). "More recently, a mutation in SLC4A4 encoding the Na+-HCO3- cotransporter NBCe1 has been identified in sisters with FHM, and a mutation in SLC1A3 encoding the glial glutamate transporter EAAT1 has been identified in one patient with pure hemiplegic migraine." (PMID 22027350, 2011). "SLC1A3 (encoding the glial glutamate transporter EAAT1) and SLC4A4 (encoding the electrogenic sodium bicarbonate cotransporter NBCe1) have been proposed as potential fourth and fifth genes (FHM4 and FHM5) responsible for pure hemiplegic migraine." (PMID 24403849, 2013).
prostate carcinoma (3 papers, 2019 to 2023). A carcinoma that arises from epithelial cells of the prostate gland. "What is known is that some of these gene products were shown to be implicated in prostate cancer progression, such as, for example, SLC7A5, SLC7A11, SLC11A1, SLC43A1 and SLC1A3." (PMID 36831650, 2023). "A member of the family, EAAT1, coded by SLC1A3, has been identified as an important contributor of resistance to ASNase in several lines of prostate cancer cells." (PMID 31998641, 2019).
Tourette syndrome (3 papers, 2018 to 2021). A neurologic disorder caused by defective metabolism of the neurotransmitters in the brain. "A functional SLC1A3 variant has been reported to be more prevalent in individuals with Tourette syndrome than controls and found to result in increased EAAT1 membrane insertion and glutamate uptake." (PMID 29741614, 2018).
acute myeloid leukemia (2 papers, 2026). Acute myeloid leukemia (AML) is a group of neoplasms arising from precursor cells committed to the myeloid cell-line differentiation. "Intriguingly, we observed that the correlation between SLC1A3 and tumor immunity in acute myeloid leukemia exhibited similarities to that in PAAD." (PMID 41234499, 2026). "Given that SLC1A3 may play a role in tumor immunity in PAAD, we further investigated its function in a single-cell RNA sequencing dataset of acute myeloid leukemia." (PMID 41234499, 2026).
colon cancer (2 papers, 2023 to 2024). "The absence of SLC1A3 resulted in the inability of cancer cells to utilize Gln, thereby inhibiting colon cancer cell growth." (PMID 39465140, 2024).
dementia (2 papers, 2021 to 2023). Loss of intellectual abilities interfering with an individual's social and occupational functions. "Among the proteins, APOE, CLU, CHL1, SLC1A3, RAB7A, and CST3 were related to the protein aggregation of misfolded proteins—causative agents and symptomatic of neurodegenerative diseases—such as α-synuclein in PD, and amyloid-β and tau in dementia." (PMID 36797805, 2023).
epileptic seizures (2 papers, 2015 to 2024). "Slc1a3 protein and mRNA levels were reported to be altered upon drug-induced epileptic seizures in animal models." (PMID 38212833, 2024).
heart failure (2 papers, 2022 to 2024). Inability of the heart to pump blood at an adequate rate to meet tissue metabolic requirements. "The second most expressed mRNA was Slc1a3, also known as GLAST1 (sodium-dependent glutamate/aspartate transporter), present in glial cells and shown to increase in the SON in conditions of heart failure and salt loading." (PMID 35685279, 2022).
hepatocellular carcinoma (2 papers, 2014 to 2025). A malignant tumor that arises from hepatocytes. "We next analyzed the prognostic implication of the HIF regulated genes involved in glutamate signaling in hepatocellular carcinoma (SLC1A1, SLC1A3, GRIA2, GRIA3 and FYN) using PROGgene to analyze the GSE 10141 mRNA expression data set from 80 surgically resected hepatomas." (PMID 25326682, 2014).
osteosarcoma (2 papers, 2009 to 2025). A usually aggressive malignant bone-forming mesenchymal neoplasm, predominantly affecting adolescents and young adults. "Expression levels of two of these "dog-like" genes (IL-8 and SLC1A3) were associated with poor outcome in human osteosarcoma patient samples." (PMID 20028558, 2009). "Validation of IL-8 and SLC1A3 protein expression in pediatric osteosarcoma tissues further supported the potential value of these novel targets." (PMID 20028558, 2009). "To validate the relevance of IL-8 and SLC1A3 in human osteosarcoma, we evaluated their protein expression in a third and distinct set of human osteosarcoma tissues by tissue microarray (TMA) immunohistochemistry, obtained from primary biopsy, definitive resection and metastases." (PMID 20028558, 2009). "Furthermore, the demonstration of IL-8 and SLC1A3 expression at the protein level in human osteosarcoma patient (TMA) samples validated the potential relevance of this comparative approach across platforms." (PMID 20028558, 2009). "Cross-species target mining identified two genes, interleukin-8 (IL-8) and solute carrier family 1 (glial high affinity glutamate transporter), member 3 (SLC1A3), which were uniformly expressed in dog but not in all pediatric osteosarcoma patient samples." (PMID 20028558, 2009).
Stroke (2 papers, 2018 to 2020). Sudden impairment of blood flow to a part of the brain due to occlusion or rupture of an artery to the brain. "In C57BL/6J mice, RNAscope in situ hybridization with probes specific for neurons (Syp), astrocytes (Slc1a3) and EphA4 (Epha4) showed that at 1 week post-stroke, Epha4 was expressed in 61% of Syp + neurons and 15% of Slc1a3+ astrocytes." (PMID 31814004, 2020).
thyroid cancer (2 papers, 2023 to 2024). "In line, knock-down of SLC1A3 reduces glutamate content and inhibits self-renewal and tumorigenicity of CD133+ thyroid cancer cells." (PMID 36768660, 2023). "Finally, a role for CD133 cancer stem cell marker in modulation of thyroid cancer metabolism has been proposed, through CD133-dependent NF-kappaB-mediated induction of aspartate/glutamate transporter SLC1A3." (PMID 36768660, 2023).
CADASIL (1 paper, 2010). "Other possible candidates include NOTCH3, the causative gene for CADASIL (cerebral autosomal dominant arteriopathy with subcortical infarcts and leukoencephalopathy), and SLC1A3, encoding the EAAT1 (excitatory amino acid transporter and glutamate transporter." (PMID 20969805, 2010).
channelopathy (1 paper, 2023). Channelopathies are a group of diseases caused by the dysfunction of ion channel subunits or their interacting proteins. "Genetic mutations in KCNA1, CACNA1A, CACNB4, SLC1A3, SCN8A, KCNMA1, and ATP1A3 genes that encode ion channels lend support to the channelopathy theory." (PMID 37008993, 2023).
Gliosis (1 paper, 2022). Gliosis is the focal proliferation of glial cells in the central nervous system. "Gliosis was studied using GFAP and GLAST (coded by the gene Slc1a3)." (PMID 36430480, 2022).
head and neck squamous cell carcinoma (1 paper, 2024). A squamous cell carcinoma that arises from any of the following anatomic sites: lip and oral cavity, nasal cavity, paranasal sinuses, pharynx, larynx, and salivary glands. "Studies have shown that aspartate and glutamate are exchanged between CAFs and head and neck squamous cell carcinoma (HNSCC) cells via the aspartate/glutamate transporter solute carrier family 1 membrane 3 (SLC1A3) channel." (PMID 39408814, 2024).
leukemia (1 paper, 2021). A malignant (clonal) hematologic disorder, involving hematopoietic stem cells and characterized by the presence of primitive or atypical myeloid or lymphoid cells in the bone marrow and the blood. "Among the metabolic genes downregulated in NPM1/cohesin-mut compared with NPM1-mut AML, CHST13, ADCY9, PRR16, LPL, and SLC1A3 were confirmed by STAG2-deficient model of NPM1-mut leukemia." (PMID 34193978, 2021).
meningioma (1 paper, 2018). A generally slow growing tumor attached to the dura mater. "RUNDC3B, SCG2, SLC1A3, EXT1 (as well as RHOBTB3, TSPAN7, CAV2, MLPH) were part of the NF2/SMARCB1 expression subclass of a recent study on genomic profiling of meningioma." (PMID 29662628, 2018).
primary immunodeficiency (1 paper, 2023). "Allograft rejection, primary immunodeficiency, and systemic lupus erythematosuswere all associated with increased SLC1A3 expression." (PMID 36911691, 2023).
progressive ataxia (1 paper, 2017). "Interestingly, while complete loss of SLC1A3 function leads to a severe phenotype with progressive ataxia, mutation in transmembrane segment 4 has been associated with partial loss of function and variable penetrance which is consistent with a late onset disease such as ALS." (PMID 29170628, 2017).
psoriasis (1 paper, 2023). An autoimmune condition characterized by red, well-delineated plaques with silvery scales that are usually on the extensor surfaces and scalp. "Consequently, breaking the cross‐talk between T cells and keratinocytes by inhibiting glutaminase (GLS), a key enzyme in glutamine metabolism, or SLC1A3, a key transporter of aspartate uptake, alleviates psoriasis in a mouse model." (PMID 36855912, 2023).
renal fibrosis (1 paper, 2023). A final common manifestation of a wide variety of chronic kidney diseases characterized by glomerulosclerosis and tubulointerstitial fibrosis. "DOCK2, SLC1A3, SOX9, and TARP were identified as potential diagnostic genes for renal fibrosis, and the most relevant immune cells were identified." (PMID 37359552, 2023). "We also found the expression of DOCK2, SLC1A3, SOX9, and TARP were higher in blood of renal fibrosis patients than healthy individuals." (PMID 37359552, 2023). "Four candidate genes namely DOCK2, SLC1A3, SOX9 and TARP were identified as biomarkers of renal fibrosis, with the area under the ROC curve (AUC) values higher than 0.75." (PMID 37359552, 2023). "The expression levels of DOCK2, SLC1A3, SOX9, and TARP were higher in the renal fibrosis group than in the control group." (PMID 37359552, 2023).
tumor (38 papers, 2009 to 2026). "Slc1a3 (Solute Carrier Family 1 Member 3; UniProt P43003) and Soga1 (Suppressor of Glucose, Autophagy Associated 1; UniProt O94964) enhance tumor metabolism and are associated with poor prognosis." (PMID 38193115, 2024). "SLC1A3, an aspartate and glutamate transporter, is abundantly expressed in cerebral and tumor tissues and is associated with immune inflammation as well as proliferation and metastasis of tumors." (PMID 36911691, 2023). "Figure EV1E shows that loss of SLC1A3 in combination of ASNase treatment impeded tumor growth." (PMID 31523835, 2019). "AI-driven in silico virtual knockout utilizing Geneformer revealed that SLC1A3 acts as a master regulator of tumor network stability." (PMID 42112375, 2026). "Drugs targeting SLC1A3 can significantly reduce tumor growth due to the close interaction and extensive metabolic remodeling between CAFs and tumors." (PMID 38218942, 2024). "Depending on the tumor site, cancer cells have increased or decreased expression of excitatory amino acid transporter 1 or 2 (EAAT1/2, SLC1A3/2) to regulate glutamate uptake for the benefit of tumor growth." (PMID 38074092, 2023). "SLC1A3 is an aspartate and glutamate transporter, mainly expressed in brain tissues, but high expression levels were also observed in some tumor types." (PMID 31523835, 2019). "Lastly, in vivo experiments indicated that SLC1A3 expression promoted tumor development and metastasis while negating the suppressive effects of ASNase by fueling aspartate, glutamate, and glutamine metabolisms despite of asparagine shortage." (PMID 31523835, 2019). "Next, we set up experiments to examine the role of SLC1A3 in tumor response to ASNase treatment in vivo." (PMID 31523835, 2019). "Tumor cells with high levels of SLC1A3 expression are resistant to glutamine starvation, and SLC1A3 depletion retards the growth of these cells in vitro and in vivo, suggesting a therapeutic potential for SLC1A3 inhibition." (PMID 30122553, 2018). "Tumor cells with high SLC1A3 expression are resistant to glutamine starvation, and SLC1A3 depletion retards cell growth." (PMID 30122553, 2018). "Among the most abundant sialoglycoproteins (median intensity >150,000) over-expressed in tumor cells, those with the largest Effect size (Effect size >5.0) include SLC1A3, PTPRZ1, GPR56 and CLU." (PMID 25360666, 2014). "SLC1A3 exhibited cytoplasmic staining in tumor and stromal cells; whereas IL8 staining was found in both osteoclasts and osteoblasts." (PMID 20028558, 2009). "SLC1A3 is upregulated simultaneously in tumor cells and CAFs, but functions differently." (PMID 38218942, 2024). "SLC1A3 is known to contribute towards tumor development in human patients with metastatic CRC." (PMID 38886847, 2024). "SLC1A3 also allows cancer cells to take up amino acids and maintains a bidirectional interaction with the tumor microenvironment which can promote hyperproliferation and tumor progression." (PMID 38886847, 2024). "We show here that depletion of SLC1A3 can retard tumor growth in vivo, raising the possibility that SLC1A3 inhibitors may be useful in cancer therapy." (PMID 30122553, 2018). "While we show an effect of SLC1A3 depletion on tumor development in xenograft models, it is possible that this may differ in immunocompetent animals or in humans." (PMID 30122553, 2018). "Thus, we conclude that SLC1A3 expression induces tumor progression and ASNase resistance." (PMID 31523835, 2019). "Decreased aspartate availability, due to inhibition of EAAT1 (SLC1A3) (system AG-), an aspartate/glutamate transporter, has been suggested to increase the vulnerability of tumor cells under low oxygen." (PMID 33511116, 2020).
tumor (continued). "Altogether, we conclude that SLC1A3 expression negates the impact of ASNase on PC3 cell survival, proliferation, and tumor growth." (PMID 31523835, 2019). "We subcutaneously implanted control and SLC1A3‐KO PC3 cells into Balb/c nude mice (cAnN/Rj) and examined tumor growth in the absence and presence of ASNase." (PMID 31523835, 2019). "Results show low to moderate tumor cell expression intensity for IL8 and SLC1A3 in most samples (66/67 (98%) and 54/64 (84%) samples have intensity scores <3 respectively)." (PMID 20028558, 2009). "Interestingly, we found an enrichment of astrocyte and cell proliferation related terms in NMF_2 and NMF_3 and the top genes include SLC1A3 and GFAP, markers of the previously defined “AC-like” tumor cell state." (PMID 40781324, 2025). "Regardless of the mechanism leading to overexpression, tumor cells expressing high levels of SLC1A3 are better able to adapt and survive under low-glutamine conditions." (PMID 30122553, 2018). "The amino acid analysis of the harvested tumor samples by mass spectrometry revealed almost complete depletion of asparagine by ASNase, regardless of SLC1A3 expression status, and slightly reduced aspartate levels in parental 4T1 cells derived tumors following ASNase treatment." (PMID 31523835, 2019).